GATA3 (GATA binding protein 3)
Diseases named in the same sentence as GATA3 in open-access papers (continued):
Sharing a sentence is not in itself a finding about the gene and the disease.
tumor (continued). "Rare tumor cells showed positivity for GATA-3 and p63 immunostains, while the plasmacytoid tumor cells exhibited loss of E-cadherin expression." (PMID 40893790, 2025). "GATA3 has emerged as a context-dependent regulator of metastasis, with both oncogenic and tumor-suppressive roles reported across cancer types." (PMID 41514651, 2025). "The tumor was strongly positive for p16 and GATA3 with a very high Ki-67 index, which strongly mimicked malignant GTNs." (PMID 40936718, 2025). "In pT2-4 carcinomas, GATA3 copy numbers were unrelated to parameters of tumor aggressiveness and patient prognosis." (PMID 39979991, 2025). "Targeting GATA3 has shown potential to impair these tumor-supporting interactions, making it a promising therapeutic target for treating HGSOC." (PMID 40330466, 2025). "The tumor cells were positive for GATA3, TRPS1, E-cadherin and the neuroendocrine markers Syn and insulinoma associated protein 1 (INSM1)." (PMID 40994809, 2025). "GATA3–METH tumours appear to be more prone to distant metastases in the brain, lung, and liver than GATA3–LOFDEL tumours." (PMID 40585280, 2025). "The tumour cells were positive for synaptophysin GATA‐3, focally positive for chromogranin, while negative for calretinin, CA9, BerEP4 and cytokeratin AE1/AE3." (PMID 40588841, 2025). "To assess spatial expression of nLc4 in the tumor context, we performed multiplex immunofluorescence staining alongside GATA3 and CK5/6, markers of luminal and basal differentiation, respectively." (PMID 40706589, 2025). "For example, the PGR and GATA3 genes concordantly showed a higher methylation pattern, resulting in a lower RNA expression in the tumor regions." (PMID 41187747, 2025). "The tumour suppressor GATA3, critical for differentiation, proliferation, and apoptosis, is similarly underutilized in basal-like therapies." (PMID 41007296, 2025). "Specifically, we observed markedly lower expression of GATA3 in tumor tissues compared to the control group." (PMID 40736702, 2025). "Collectively, our results position GATA3 as a potential molecular node connecting host signaling, viral transcription, and tumor formation." (PMID 41585508, 2025). "We identified its role in tumor progression by regulating lncRNAs such as XLOC_006941, in line with previous studies linking GATA3 to metastasis." (PMID 39941924, 2025). "Tumor cells typically exhibit positivity for broad-spectrum epithelial markers such as GATA3, epithelial membrane antigen (EMA), AE1/AE3, CK7, and CK8, supporting their urothelial origin." (PMID 40677482, 2025). "IHC markers showed varying positivity rates across different tumor types, with GATA-3, CDX2, and TTF1 proving particularly useful in distinguishing the tumor origin." (PMID 40751531, 2025). "In the second analysis, we compared the group of tumours with LOF mutations or copy number deletions of GATA3 (this group was called GATA3–LOFDEL) with the same control group of tumours GATA3–CTRL." (PMID 40585280, 2025). "M2 macrophages, known for their immunosuppressive and tumor-promoting roles, release EVs that transfer GATA3 to OC cells." (PMID 40330466, 2025). "Positive staining for CK7, p63, CK AE1/AE3, ER, and GATA3, combined with low Ki-67 proliferation (<5%), supports the diagnosis of a benign extraovarian Brenner tumor with transitional-type epithelium." (PMID 40700236, 2025). "While existing research has reported the utility of DTI parameters in tumor grading and Ki-67 prediction, systematic analyses combining GATA3 expression and DTI parameters are still in the exploratory stage." (PMID 40881878, 2025). "The PCA projection shows that the GATA3–METH and GATA3–LOFDEL tumours correspond to two well-separated populations." (PMID 40585280, 2025). "Our GATA3 deletion rate of 1.1% was in the lower range of previous studies reporting 0.2–38% GATA3 deletions obtained by methods which are more dependent on tumor cell purity and thresholds for defining deletions such as CGH, aCGH, and LOH analysis." (PMID 39979991, 2025).
tumor (continued). "BEAS-2B LTR-env xenografts exhibited faster tumor growth when GATA3 was overexpressed, whereas knockdown diminished tumor size." (PMID 41585508, 2025). "In vivo, GATA3 overexpression promoted LTR-Env–induced tumor formation in nude mice, whereas GATA3 interference suppressed tumor growth." (PMID 41585508, 2025). "Twenty-one cases which demonstrated positive GATA3 expression with scattered or basal strips of CK5/6 staining in < 10% tumour population were included in the luminal subtype." (PMID 39856762, 2025). "In cancer, GATA3 influences tumor development and progression by affecting cancer cell behavior within the tumor microenvironment (TME)." (PMID 39768217, 2024). "All 4 demonstrated diffuse strong positivity for mammaglobin, GATA3, and S100, as well as expression of vimentin in more than 25% of tumor cells." (PMID 37306115, 2024). "In vivo and in vitro validations demonstrate that truncating just 6 key residues in GATA3 disrupts phase separation, enhancing tumor cell migration and inhibiting growth." (PMID 38531854, 2024). "Immunohistochemical stains performed on the lung tissue demonstrated that the tumor cells were diffusely immunoreactive for hPL, Gata3 and AE1/AE3, and had only rare hCG-positive cells and rare p63-positive cells." (PMID 38172961, 2024). "Among the 991 BC tumor samples, GATA3 had the highest frequency of somatic SNVs, accounting for 13%; followed by FOXA1, accounting for 3%; AGR2, CA12, CEP55, CDC20, TBC1D9, and MELK had very few somatic SNVs." (PMID 39440050, 2024). "Collectively, we showed that deleting key residues disrupts GATA3’s phase separation and affects tumor cell function." (PMID 38531854, 2024). "Among them, the highest numbers of tumor samples expressed GATA3, CK7, PCK, CK5, GCDFP15 were 25 (43%), 21 (36%), 19 (33%), 13 (22%), and 10 (17%) respectively." (PMID 38750402, 2024). "The tumor cells showed diffuse expression for GATA3, ER/PR, supporting the diagnosis of metastatic ILC." (PMID 39076998, 2024). "In this space, the tumor cells were readily distinguishable from the remaining cells by the basal marker Keratin 5 or the expression of either the luminal marker GATA3 or other keratin proteins." (PMID 38499531, 2024). "Immunopositivity for GATA3 in a head and neck tumor is suggestive of a salivary gland origin of the tumor process." (PMID 38929710, 2024). "Accordingly, GATA3 is differentially expressed in different tumor types and stages; therefore, targeting GATA3 for cancer therapy is variable." (PMID 39768217, 2024). "As a noncanonical m6A methyltransferase, high expression of KIAA1429 in HCC SK-Hep1 and HCCLM3 cells mediates m6A methylation of the mRNA of GATA binding protein 3 (GATA3) precursor; this decreases the levels of GATA3 and promotes tumor growth and metastasis." (PMID 38566136, 2024). "Evidence indicated the association between GATA3 expression and the reversal of EMT that dampens tumor metastasis." (PMID 39768217, 2024). "Our study also highlighted the decreased type 2 identity of tILC2s through scRNA sequencing during tumor progression, as GATA3 gene expression decreases due to the presence of growing tumor in a mouse body." (PMID 38524132, 2024). "Depletion of Gata3 sensitized tumor cells to PARP inhibitor (PARPi), and reconstitution of Gata3 enhanced resistance of Brca1-deficient tumor cells to PARP inhibitor." (PMID 38627785, 2024). "Noticeably, the necessity of determination of GATA3 expression in BC is not limited to tumor stratification and molecular subtyping, as it is crucial for therapeutic designation and combination treatment plans." (PMID 39768217, 2024). "Especially p63 positive tumours behaved independently of their GATA3 status, and the same tendency was also seen for the smaller group of p63 negative cancers." (PMID 39539567, 2024).
tumor (continued). "Depletion of Gata3, similar to Brca1 depletion, sensitizes tumor cells to PARP inhibitor-induced cell death." (PMID 38627785, 2024). "USP21 is known to deubiquitinate and stabilize several transcription factors such as YY1, FOXM1, EZH2, Nanog, and GATA3, promoting cancer cell proliferation, migration, and invasion and in vivo tumor growth." (PMID 39305962, 2024). "GATA3 (GATA Binding Protein 3) acts as a tumor suppressor by activating the transcription of E-cadherin and inhibiting the epithelial–mesenchymal transition (EMT) and metastasis." (PMID 39456252, 2024). "GT3-INCP significantly enhances cell proliferation and tumor growth, an effect that is facilitated by its interaction with GATA3, a key transcription factor involved in the development of luminal epithelial cells." (PMID 39333489, 2024). "Elevated MI within the TME has been shown to reduce GATA3 levels, correlating with advanced tumor grade and poorly differentiated forms of BC." (PMID 39768217, 2024). "This association with good tumor behavior, including in BCC, can be explained by the crucial role played by GATA3 in developing epithelial structures in both embryonic and adult tissues and in promoting cell differentiation in many tissues, including skin." (PMID 38668712, 2024). "As a transcription factor that regulates cell differentiation and inhibits tumour proliferation, GATA binding protein 3 (GATA3) is repressed by overexpressed KIAA1429 leading to HCC cell proliferation." (PMID 38711100, 2024). "In conclusion, higher GATA3 expression was significantly associated with a more indolent BCC histological type, higher BCL2 expression, and a higher stromal tumor-infiltrating lymphocyte count." (PMID 38668712, 2024). "Although BRCA1 mutation carriers rarely develop ER+ tumors, in our model, tumors were heterogenous with a fraction of tumor cells expressing ERα and GATA3." (PMID 38059556, 2024). "The miR-18a/low tumours had higher expression of the luminality-associated genes like ESR1, GATA3, FOXA1, XBP1 and TFF1 and a lower expression of the basality-associated genes such as KRT18, KRT17, FOXC1, ANLN, STIL and MIA (p < 0.05)." (PMID 38786043, 2024). "Positive staining of GATA-3 in the pathologic report supported the assertion of breast origin for the tumor." (PMID 39022491, 2024). "This interaction between GT3-INCP and GATA3 leads to the cooperative regulation of estrogen-responsive and tumor-promoting genes, including MYB and PDZK1." (PMID 39333489, 2024). "The enforced GATA3 expression in prostate tumors interferes with Akt signaling and maintains a differentiated prostatic duct phenotype that is predictive of low tumor recurrence." (PMID 39768217, 2024). "Conversely, IL-33 signaling encourages the proliferation of suppressive CD4+ Foxp3+ GATA3+ Treg cells, especially in tumor-specific environments high in IL-33." (PMID 40236667, 2024). "Immunohistochemically, the neoplastic cells of main tumor were diffusely immunoreactive for hPL, Gata3 and AE1/AE3, and had only rare hCG-positive or p63-positive cells." (PMID 38172961, 2024). "Consistently, the expression of CtIP in Gata3+/− tumor cells was lower than in Gata3+/+;Brca1+/+ cells." (PMID 38627785, 2024). "Previous studies have demonstrated that the tumor microenvironment (TME) has a significant impact on GATA3 expression." (PMID 39768217, 2024). "Despite that, in the present study, among four samples presenting GATA3 alterations, one luminal A tumor also presented an activated PIK3CA." (PMID 39208653, 2024). "Knockdown of Gata3 in MMTV-PyMT luminal tumor cells also drastically enhanced the number of cells with DNA DSBs in tumorigenesis." (PMID 38627785, 2024). "We determined tumor cell proliferation in vivo and observed that the percentages of Ki-67-positive cells were comparable in p18−/− and p18−/−; Brca1+/− or p18−/−; Gata3+/− tumors." (PMID 38627785, 2024).
tumor (continued). "Analytical evaluation of the correlation of the GATA3 expression with clinicopathological features revealed that the GATA3 expression decreased (p < .001, p < .0001) as the grade and stage increase (namely tumor progression)." (PMID 38173189, 2024). "How loss-of-function of GATA3 regulates EMT and mammary CSCs in tumor initiation and progression remain elusive." (PMID 37353480, 2023). "We transduced two independent p18mt;Gata3+/− tumor cell lines with pEZ-Lv201 (Empty) and pEZ-Lv201-c-Fos (c-Fos), thereby establishing empty- and c-Fos-expressing stable cells." (PMID 37353480, 2023). "Data including age and sex, tumor grade, tumor size, types of invasion, GATA-3, and GCDFP-15 were assessed." (PMID 37383162, 2023). "A high expression level (mfIHC score) of PR, AR, GATA3, and TROP2 was significantly linked to low pT stage and low tumor grade (p ≤ 0.0002 each)." (PMID 38137396, 2023). "The Cancer Genomic Atlas (TCGA) database analysis for HGSOC patients revealed that GATA3 is much more prevalent in the TME than in the tumor purity." (PMID 37039909, 2023). "On the other hand, patients with a pre-BCG tumor microenvironment polarized to Th-2 (GATA-3+) were responders to BCG due to the shift in the immune polarization that activated a massive influx of inflammatory cells." (PMID 38067259, 2023). "In this report, nearly all tumor cells were positive for GATA-3, KRT7, EMA, E-Cadherin, Ksp-Cadherin, 34βE12, and AMACR in varying intensities, focally positive for CD10 and Vimentin, while negative for CD117, TFE3, RCC, and CAIX." (PMID 37143937, 2023). "For instance, KIAA1429 promotes tumor growth and metastasis by reducing downstream gene GATA3 expression in LIHC." (PMID 37606975, 2023). "Depletion of Gata3 in luminal tumor cells also up- and downregulates Fra1 and c-Fos, respectively, leading to the activation of EMT and promotion of tumorigenesis." (PMID 37353480, 2023). "As expected, the majority of Ba/Sq tumours in the consensus classification scheme showed a typical CK5/6 + /GATA3-/CK20- expression phenotype." (PMID 36944729, 2023). "Many studies have suggested that GATA3 plays an important role as a tumor suppressor in the prevention of urothelial cancer progression and metastasis." (PMID 37629741, 2023). "We investigated GATA3 immunohistochemical expression rates and performed a subgroup analysis based on tumor site, study location, and histological subtypes." (PMID 37629741, 2023). "Luminal tumours, accounting for about 50% of MIBCs, present high expression of urothelial differentiation markers (GATA3, FOXA1, KRT20, uroplakins) and are enriched in activating mutations of FGFR3." (PMID 36944729, 2023). "Spearman analysis demonstrated a significant positive correlation between GATA3 expression and the extent of tumor-infiltrating resting mast cells in the tumors (R= 0.33, p<0.0001)." (PMID 37900131, 2023). "A recent study confirmed that GATA3 was abundantly released from TAMs via exosomes, contributing to tumor development in the TME." (PMID 37039909, 2023). "Using an integrated analysis of RNA-seq and ChIP-seq data in ER+ BC cells, together with TCGA data, the authors identified the common direct targets of GT3-INCP/GATA3 that are important for mediating their tumor-promoting function." (PMID 36856112, 2023).
tumor (continued). "Examination of the molecular role of the protease within Luminal A tumours, revealed that CTSV promotes tumour cell invasion and proliferation, in addition to degradation of the luminal transcription factor, GATA3, via the proteasome." (PMID 38026973, 2023). "We transplanted these tumor cells into mice and although all mice received 1 × 104 Fra1- and control-knockout p18mt;Gata3+/− tumor cells, tumors generated by Fra1-knockout cells were tiny and significantly smaller than those generated by control cells." (PMID 37353480, 2023). "To explore the connection between mast cell infiltration and GATA3 within tumor tissue, we conducted single-cell sequencing analysis and employed the TISCH database." (PMID 37900131, 2023). "Tumor was resected and analyzed by H&E staining and expression of luminal markers estrogen receptor alpha (ERα), GATA3, and FOXA1 and cytokeratins CK5/6, CK8, CK14 and CK19 was examined." (PMID 37709737, 2023). "GATA-3 (p < 0.001), tumor size (p < 0.001), lymph node (LN) metastasis (p < 0.001), clinical stage (p = 0.002), histological grade (p < 0.001) and Ki-67 (p < 0.003) displayed significant associations with survival." (PMID 37483298, 2023). "Immunohistochemistry revealed that the tumor cells diffusely and strongly expressed cytokeratin, synaptophysin, chromogranin A, GATA3, CAM5.2, and estrogen and progesterone receptors; partially expressed AR and GCDFP15." (PMID 38115331, 2023). "Using rescue experiments, the authors showed that the interaction between GT3-INCP and GATA3 was important for mediating the tumor-promoting function of GT3-INCP." (PMID 36856112, 2023). "We performed IHC staining that showed the tumor cells in mass (I) diffusely and strongly expressed GATA3, MUC1, EMA, E-cadherin, 34bE12, Ksp-cadherin, CK7, and PAX-8, while CD117, CAIX, CK20, RCC, and TFE3 were negative." (PMID 37924117, 2023). "We observed that depletion of Gata3 in tumor cells reduced the expression of c-Fos, ERα, and E-Cad but enhanced the expression of Fra1 and Vim." (PMID 37353480, 2023). "We infected p18mt;Gata3+/− tumor cells with pLvx-Flag (Empty) and pLvx-Flag-Gata3 (Gata3), respectively, and established Empty and Gata3 stably expressing cells." (PMID 37353480, 2023). "Higher indices of GATA-3 expression were found to be significantly related to improved clinical-pathological parameters, smaller tumor sizes, lower grades, and higher survival rates." (PMID 37483298, 2023). "Next, we generated empty- and Gata3-expressing p18mt;Brca1+/− tumor cells, as previously reported, and performed similar analysis as for p18mt;Gata3+/− tumor cells." (PMID 37353480, 2023). "The results indicated that dogs with tumours with a high GATA-3 expression also had a significantly higher survival rate than those with low GATA-3 expression (p < 0.0001, HR 5.021 and 95% CI 1.741–14.48), and presented a median survival of 740 days." (PMID 37483298, 2023). "Here, we found the higher expression of GATA3 indicated a better prognosis, which was supported by a previous analysis that GATA3 was required for homologous recombination repair and served as a tumor suppressor." (PMID 37996875, 2023). "Herein, we have described the role of increased GATA3 expression by tumor cells from early-stage (non-invasive) UC of the urinary bladder and its relation to local recurrence, independent of gender, age, tumor differentiation, and stage." (PMID 37829946, 2023). "We knocked out Fra1 in p18mt;Gata3+/− tumor cells and observed that Fra1 knockout drastically reduced the expression of the EMT markers Vim, Snail, Twist, Slug." (PMID 37353480, 2023). "GATA3 is probably one of the most sensitive markers of BC, but is expressed in numerous other types of tumours, including the majority of urothelial carcinomas, and other cancers." (PMID 37012444, 2023). "Immunohistochemistry showed that the tumor cells diffusely and strongly expressed cytokeratin, synaptophysin, chromogranin A, GATA3, and CAM5.2." (PMID 38115331, 2023).